BRCA2 (BRCA2 DNA repair associated)
Diseases named in the same sentence as BRCA2 in open-access papers (continued):
Sharing a sentence is not in itself a finding about the gene and the disease.
breast cancer (continued). "Furthermore, transcriptional activity of BRCA1 and BRCA2 genes has been observed in multiple breast cancers (including MCF-7 cells)." (PMID 32010625, 2019). "Moreover, LST score, mutational signature 3, NtAI score and Myriad score detected bi-allelic inactivation of PALB2 and of BRCA1/BRCA2 in PALB2-associated breast cancers and in BRCA1/2-associated breast cancers, respectively, with comparable accuracy." (PMID 31428676, 2019). "Finally, it has also been found that RANKL and RANK are highly expressed in pre-malignant lesions, as well as in breast cancer samples from both BRCA1 and BRCA2 human mutation carriers." (PMID 30621730, 2019). "However, most women (87%) incorrectly agreed “that about half of all breast cancers are caused by mutations in BRCA1 and BRCA2”." (PMID 31270367, 2019). "Regarding the difference found in the family history of women with mutations in BRCA1 or BRCA2 genes, we can observe that BRCA1 mutated families showed a higher frequency of bilateral breast cancer (OR=4.96 vs. OR=1.67) and presence of ovarian cancer (OR=4.32 vs. OR=1.63)." (PMID 31244284, 2019). "The current results suggest that regarding breast cancer-specific mortality, BC surveillance may be a reasonable and balanced alternative to BRRM for BRCA2 mutation carriers." (PMID 31302855, 2019). "For the same reasons, the presence of double mutations of BRCA1 and BRCA2 is extremely rare in the general population, although not exceptional in Ashkenazi breast-cancer patients." (PMID 29346284, 2018). "By contrast, the mutations p.3076E and p.Y3092C in BRCA2 were detected in patients with luminal B and luminal A breast cancer, respectively, and had not been previously reported in the Polish population." (PMID 30040829, 2018). "We found no clear evidence that either BRCA1 or BRCA2 germline mutations significantly affect overall survival with breast cancer after adjusting for known prognostic factors." (PMID 29337092, 2018). "We first compared the performance of PAFA, Eigen, CADD, GWAVA, FATHMM-MKL, and DANN on prioritizing coding variants from five well-studied genes (MLL2, CFTR, BRCA1, BRCA2, and TERT) associated with Kabuki syndrome, cystic fibrosis, breast cancer, or aggressive thyroid tumor, respectively." (PMID 29996888, 2018). "Hence, our aims were to characterize a group of Brazilian patients with early onset breast cancer for BRCA1 and BRCA2 germline mutations, as well as for somatic SNVs arising in luminal subtype tumors." (PMID 29854292, 2018). "Others have been recently approved for the treatment of specific breast cancer subtypes, such as the mTOR inhibitor everolimus in advanced luminal breast cancer and the poly(ADP-ribose)polymerase (PARP) inhibitor olaparib in metastatic breast cancer with germline BRCA1 or BRCA2 mutations." (PMID 30038706, 2018). "A later age at menarche and breastfeeding are protective for BRCA1-associated breast cancer, but do not appear to influence risk in women with a BRCA2 mutation." (PMID 30572612, 2018). "It directly targeted BRCA2 and suppressed its translation in breast cancer." (PMID 29891014, 2018). "These genes included PALB2, BRCA2, and ATM, which are associated with breast cancer risk." (PMID 29706558, 2018).
breast cancer (continued). "Furthermore, we also used a PTV-ALFRED model to analyze each of the 17 cancer types and three genes were significant in at least one individual cancer type (FDR = 0.2, four associations: BRCA2 and ATM in breast cancer, BRCA1 and BRCA2 in ovarian cancer)." (PMID 29973584, 2018). "We aimed to identify novel genetic variants in prospectively detected breast cancer (BC) or gynecological cancer cases tested negative for their families’ pathogenic BRCA1/2 variant (path_BRCA1 or path_BRCA2)." (PMID 29371908, 2018). "BRCA1, BRCA2 and CHEK2 are known breast cancer predisposition genes." (PMID 29678143, 2018). "In summary, these results indicate a strong anti-tumor effect of the everolimus+olaparib combination in the BRCA2 basal-like breast cancer PDX HBCx-17, with evidence of increased DNA damage in all treatment arms and inhibition of key component of the homologous recombination pathway." (PMID 30038706, 2018). "In this report, case 2, with both BRCA1 and BRCA2 germline mutations, showed high response of platinum-based chemotherapy for lymph node recurrence and long-term survival after the recurrence, in a manner similar to BRCA1/2-mutated ovarian and breast cancers." (PMID 31608315, 2018). "BRCA1-associated breast cancers exhibit the pathological features of an aggressive phenotype, and are usually hormone receptor-negative, whereas BRCA2-assocated breast cancers tend to resemble sporadic cancers, and are predominantly hormone receptor-positive." (PMID 30572612, 2018). "The most common breast cancer predisposing syndrome is hereditary breast and ovarian cancer syndrome (HBOC) that is related to pathogenic germline variants in BRCA1 (OMIM 113705) and BRCA2 (OMIM 600185) genes." (PMID 29868112, 2018). "Similarly, patient 12 (NTM-BCa-12) with a history of alcohol consumption who was diagnosed with NTM (MAC) at age 55 and stage-IB breast cancer at age 61 exhibited numerous somatic and germ line BRCA1 and BRCA2 mutations in the sputum." (PMID 30054559, 2018). "Within a breast cancer biobank research study, ten germline mutations in BRCA1 (n = 5) or BRCA2 (n = 5) were incidentally revealed in study participants that were themselves not aware of their mutation carrier status, 5–7 years after they had been included in the study." (PMID 29082482, 2018). "While most BC are sporadic in nature, approximately 5–10% are attributed to genetics, arising from autosomal dominant mutations in specific cancer genes, the strongest of which are the two breast cancer susceptibility genes BRCA1 and BRCA2 (collectively named “BRCA”)." (PMID 29782524, 2018). "Furthermore, the biological pathways ‘Role of BRCA1, BRCA2 and ATR in Cancer Susceptibility’ and ‘Breast Cancer’ were found in the top enriched terms for NA and SA regions with a p of 1.074×10−8 (2.09×10−10) and 2.804×10−5 (2.69×10−3), respectively." (PMID 30263132, 2018). "In contrast to BRCA-1 tumours, breast cancer arising from BRCA2 mutation do not differ from sporadic cancer with regard to distribution of breast cancer subtypes, the luminal forms expressing estrogen and progesterone receptors being the most frequent." (PMID 30544963, 2018). "In contrast, genotyping of Italian families with an aggregation of melanoma and breast cancer revealed the absence of BRCA2 mutations, which does not exclude the link between BRCA2 and melanoma but suggests it is not common." (PMID 30286154, 2018). "When ductal lavage was performed on asymptomatic BRCA1/2 mutation carriers, the cells within the lavage fluid of 8/19 women showed promoter hypermethylation of at least one of four genes (BRCA1, BRCA2, ERα, and RARβ2) that are often hypermethylated in breast cancer." (PMID 29614786, 2018). "Inactivating mutations of BRCA1 and BRCA2 frequently occur in breast cancer as well, while unique mutations in GATA3, PIK3CA, and MAP3K1 are enriched in the luminal A subtype of breast cancer." (PMID 29753129, 2018).
breast cancer (continued). "Poly(adenosine diphosphate [ADP]-ribose) polymerase (PARP) inhibitors have shown an impressive safety profile and anti-tumor efficacy in patients with breast cancer 1 and 2 (BRCA1 and BRCA2) gene-mutated ovarian cancer who were previously treated with the standard of care chemotherapy." (PMID 30050740, 2018). "The risk of breast cancer for BRCA2 mutation carriers was not evaluated, given the lack of evidence for an effect in earlier reports." (PMID 30572612, 2018). "We showed that for BRCA1 and BRCA2 mutation carriers breast cancer risk was not increased after exposure to ovarian stimulation for IVF." (PMID 29937543, 2018). "Mutation screening in the family carrying BRCA2:p.Glu1413Aspfs revealed two additional carriers of RNASEL:p.Glu265*: the proband’s mother, who had been diagnosed with breast cancer and leukemia (age at diagnoses 65 and 83 years respectively) and one of the proband’s brothers." (PMID 29422015, 2018). "In a recent meta-analysis of the literature, tamoxifen use for the treatment of a first breast cancer resulted in a significant 44% risk reduction of a second breast cancer in both BRCA1 and BRCA2 mutation-positive patients combined (summary HR = 0.56; 95% CI 0.41–0.76)." (PMID 30572612, 2018). "By contrast, double heterozygosity of mutations in the DNA repair genes BRCA1 and BRCA2 in patients with breast cancer was found to be no more deleterious than a single heterozygous mutation." (PMID 29706558, 2018). "Some Nigerian patients with breast cancer were previously screened for a few specific alleles of BRCA1 and BRCA2,5-8 but no African population has been evaluated for all known and candidate breast cancer genes." (PMID 30130155, 2018). "In breast cancer, germline mutations in BRCA1 and BRCA2 genes may support the carcinogenic process in around 20% of the young patients, but only in 1-4% of post-menopausal women." (PMID 29854292, 2018). "The BRCA2 E1308X mutation was originally described in two independent families in Spain, each with three or more breast cancer cases, but without ovarian cancer." (PMID 30400234, 2018). "The risk of breast cancer in the first-degree relatives of BRCA1 and BRCA2 probands was significantly higher than in first-degree relatives of non-carrier families (hazard ratio, HR=3.31, 95% CI 2.46-4.44, p<0.001; HR=3.31, 95% CI 2.46-4.44, p<0.001 for BRCA1 and BRCA2 respectively)." (PMID 29861850, 2018). "Although everolimus is approved only in ER+ breast cancer, it could be of potential interest to validate this drug combination in BRCA2 basal-like tumors." (PMID 30038706, 2018). "Indeed, HGSOC with diminished BRCA1 or BRCA2 expression typically have increased sensitivity to DNA damaging chemotherapeutics and restoration of BRCA1 in a BRCA1 deficient breast cancer cell line decreased cisplatin sensitivity in a xenograph model." (PMID 29973223, 2018). "In addition, anti-cancer therapy which combine PARP inhibition and genotoxic chemotherapeutic agents according to the expression of PARP1, γH2AX, BRCA1, and BRCA2 has been suggested for breast carcinomas and Ewing sarcomas." (PMID 29784019, 2018). "In another study, women lacking functional BRCA1/BRCA2 at increased breast cancer risk also show greater risk for heart disease and metabolic diseases." (PMID 28698603, 2017). "The number of non-proband women diagnosed with breast cancer was too small to estimate the penetrance of BRCA2 mutations (two non-proband cases), and separate BRCA1 mutations (n = 7 for 3450del4 and n = 3 for A1708E)." (PMID 28680148, 2017).
breast cancer (continued). "Treating BRCA-mutant breast cancers with PARP inhibitors improved patient outcome, so PARP inhibitors may also show increased effectiveness in bladder tumors with BRCA2 or other FA mutations." (PMID 29263839, 2017). "Worse survival outcomes have been reported in BRCA2-mutated breast cancer (but not BRCA1) compared to sporadic cancers, independent of treatment, in some population-based studies, which seems to be due to adverse tumour characteristics." (PMID 29069866, 2017). "Disease-associated variants are mainly protein-truncating mutations, whereas a few missense substitutions are reported to perturb its interaction with breast cancer susceptibility proteins BRCA1 and BRCA2, which play essential roles in homology-directed repair (HDR)." (PMID 29387807, 2017). "In breast cancer, this mostly involves defective repair of DNA double-stranded breaks by homologous recombination (HR), e.g. as is known to occur in tumor cells arising in carriers of either BRCA1 or BRCA2 germline mutations." (PMID 28679371, 2017). "A recent meta-analysis did not detect differences in breast cancer specific survival rate in BRCA2 mutation carriers when compared to sporadic ones." (PMID 28985233, 2017). "AR has been shown to be expressed in 80% of BRCA2 mutated breast cancer as opposed to only 30% of BRCA1 mutated breast cancer." (PMID 28863181, 2017). "Approximately 5-10% of breast cancer cases and 10%-15% of epithelial ovarian cancer cases develop due to single gene mutations that are passed down in the family, such as the breast cancer 1 (BRCA1) and breast cancer 2 (BRCA2) genes." (PMID 28931501, 2017). "A second female sibling of this patient had inherited the ATM frameshift but not the BRCA2 K3326* variant, and developed breast cancer at the age of 46." (PMID 28591191, 2017). "All breast cancer PRSs derived from population-based study results (available online) were statistically significantly associated with breast cancer risks for both BRCA1 and BRCA2 carriers." (PMID 28376175, 2017). "Even though all females who acquire a BRCA1 or BRCA2 variant do not essentially cause breast cancer, it is uncertain what other determinants such as genetic or environmental persuade the risk of breast." (PMID 28969709, 2017). "In addition to breast cancer, males with BRCA1 or BRCA2 pathogenic variants face increased lifetime risks for prostate and pancreatic cancers." (PMID 28008555, 2017). "Among these, rare monoallelic LoF variations within the PALB2 gene (partner and localiser of BRCA2) are associated with breast cancer at a risk two to four times that among non-mutation carriers." (PMID 28449691, 2017). "Based on their five and ten year figures for breast cancer free survival and overall survival after ovarian cancer, the authors suggest non-surgical management of breast cancer risk in women with a BRCA1/BRCA2-associated ovarian cancer." (PMID 28780755, 2017). "None of the BRCA2 variants were significantly associated with breast cancer risk either in the overall cohort, or when stratified by ethnicity." (PMID 28222693, 2017). "Studies and meta-analyses of breast cancer cases have shown that BRCA1 with or without BRCA2 mutations is linked to a poor outcome." (PMID 29152070, 2017). "Particularly in breast cancer, the majority of the known susceptibility genes encode proteins with integral roles in DNA damage response (DDR), including the two major ones BRCA1 and BRCA2, and a number of others, such as PALB2, ATM and CHEK23–5." (PMID 28386063, 2017). "Inhibition of estrogen receptor function decreases breast cancer risk in healthy BRCA2 mutation carriers, but not in BRCA1 mutation carriers." (PMID 28977823, 2017).
breast cancer (continued). "The lack of pathogenic variants in BRCA1, BRCA2 and other predisposition genes indicates that these five families are all BRCAx breast cancer family." (PMID 28076423, 2017). "In this way, risk-reducing surgery was raised as having been proven to reduce breast cancer risk in BRCA1/BRCA2 carriers, but also as something not usually considered when the focus is on ovarian cancer treatment." (PMID 28780755, 2017). "This type of unselected genetic testing in newly diagnosed women with epithelial ovarian cancer is leading to more families without a strong history of breast cancer being found with germline BRCA1/BRCA2 mutations." (PMID 28780755, 2017). "MS-MLPAs were performed to assess BRCA1 and BRCA2 methylation in breast carcinoma tissues from 39 BRCA1 and 33 BRCA2 germline mutation carriers, 80 patients with sporadic breast cancer, and normal breast tissues from 5 BRCA1 and 4 BRCA2 mutation carriers and 5 nonmutation carriers." (PMID 28569220, 2017). "No pathogenic variants in BRCA1, BRCA2 and other classical breast cancer-predisposition genes were present in these five families." (PMID 28076423, 2017). "Understanding the relationship between germline and tumour genetics is important in patients where early-onset familial breast cancer or differences in drug response and survival outcome cannot be explained by mutations in the major tumour suppressor genes, BRCA1 and BRCA2." (PMID 28241424, 2017). "Moreover, prophylactic salpingo-oophorectomy protects patients with breast cancer who are also BRCA1/BRCA2 carriers from developing ovarian cancer." (PMID 26928677, 2016). "Further support was provided by our in silico analysis showing that BRCA1 candidate proteins, when mapped to mRNA transcripts, could cluster BRCA1- and BRCA2-related breast cancer cases." (PMID 27566577, 2016). "In BRCA2 mutation carriers the cumulative risk of male breast cancer at age 70 years has been estimated 6.8 %, but evidences for a correlation between the location of the mutation within BRCA2 gene and risk of male breast cancer are still lacking." (PMID 26852130, 2016). "Utilizing SYBR Green based real-time allele-specific PCR, we have analyzed DNA samples of patients with breast cancer and disease free controls to identify the following BRCA1 and BRCA2 mutations: BRCA1 5382insC, BRCA1 4153delA, BRCA1 185delAG, BRCA1 300T>G, BRCA2 6174delT." (PMID 29138730, 2016). "Germline mutations in the BRCA1 and BRCA2 genes in patients with early-onset breast cancer have not been clearly identified within the Algerian population." (PMID 26997744, 2016). "About 20 % of hereditary breast cancers are caused by mutations in BRCA1 and BRCA2 genes." (PMID 26852130, 2016). "Thus, RANK is highly expressed in pre-malignant lesions as well as in breast cancer that has developed in BRCA1 and BRCA2 mutation carriers." (PMID 27241552, 2016). "Currently, BRCA1 or BRCA2 mutation carriers with breast cancer do not receive specific treatment targeting the defect in their tumor, despite strong preclinical and promising clinical evidence." (PMID 27323902, 2016). "This is in contrast to the second most common hereditary breast cancer, BRCA2-related breast cancer, which has a significantly different gene expression profile and is typically lower grade, is more differentiated, appears later in life, and belongs to the luminal/ER-positive subtype." (PMID 27708239, 2016). "In the breast cancer group, one woman carried a BRCA1 mutation and one woman a BRCA2 mutation." (PMID 27028854, 2016).